TNF (tumor necrosis factor)
Diseases named in the same sentence as TNF in open-access papers (continued):
Sharing a sentence is not in itself a finding about the gene and the disease.
asthma (continued). "Decreasing TNFα may reduce airway inflammation and eosinophil recruitment, potentially influencing asthma in obese patients, who might respond better to leukotriene modifiers than to inhaled corticosteroids during asthma exacerbations." (PMID 39407941, 2024). "In this sense, asthma is a respiratory disease characterized by a chronic inflammation including the activation of the Th2 cell response to allergens, and is often found to have elevated levels of inflammatory cytokines including IL-4, IL-5, IL-13, TNF-α, and IL-1β, among others." (PMID 38792145, 2024). "In addition, asthma is related to the airways’ persistent inflammation, and for example, tumor necrosis factor-α, IL-4, transforming growth factor-β, IL-6, and vascular endothelial cell growth factor are all involved in the inflammatory response of asthmatic lungs as well as airway remodeling." (PMID 38594768, 2024). "The data showed positive correlations between IgE levels and both IFN-α (rh = 0.26, p = 0.04) and TNF-α (rh = 0.29, p = 0.02), suggesting possible interactions between allergic and inflammatory pathways, as described in McIntyre and Viswanathan’s work on asthma phenotype complexity." (PMID 39727498, 2024). "Thus, our study suggests the concept that drugs aimed at cytokines, such as IL-17 and TNFα, known here to correlate with neutrophilic inflammation in obese asthma, may lead to novel therapeutic interventions in these patients." (PMID 38892358, 2024). "However, targeting TNFα has not been successful in asthma clinical trials and is associated with adverse events." (PMID 39194521, 2024). "Since ER stress/UPR pathway is involved in asthma development and TNFα activates this pathway in several cell types, we investigated whether TNFα activates ER stress/UPR pathway in primary human lung fibroblasts and whether asthmatic lung fibroblasts have dysregulated responses." (PMID 36760534, 2023). "Furthermore, previous research in asthma patients proved exogenous supplementary choline as an anti-inflammatory factor inducing lowered levels of pro-inflammatory cytokines, including IL-4, IL-5, and TNF-α, which are also involved in T1D." (PMID 40303249, 2023). "Many MCs mediators (PGD2, leukotriene C4 LTC4, IL-6, IL-13, TNF-α, tryptase, and chymase) interact with the epithelium, leading, altogether, to mucus hypersecretion by hyperplastic submucosal glands and epithelial goblet cells, which is a known key feature, especially in severe asthma." (PMID 37298721, 2023). "Thus, downregulating the TNF/NF-κB pathway could be a therapeutic strategy for alleviating lung inflammatory diseases such as asthma and COPD." (PMID 37108390, 2023). "However, non-Th2 cytokines, including TNF-α, can also mediate Th2-low asthma." (PMID 37153575, 2023). "However, the mechanism in which TNF-a acts in mucus secretion, airway hyperreactivity, and airway remodeling of human asthma remains unclear." (PMID 35359966, 2022). "In respiratory diseases and asthma, cytokines promote the survival of inflammatory cells, contributing to the maintenance of chronic inflammation and producing proinflammatory cytokines such as IL-1β, IL-6, and TNF-α, which are increased in the sputum and BALF of patients with asthma." (PMID 36555240, 2022). "Also, Pro-inflammatory cytokines such as TNF-α, IL-1β, and IL-6 increase in asthma." (PMID 36076196, 2022). "In a murine model of asthma, exposure to NP (5 and 500 μg/kg bw∙day) in both bone-marrow derived dendritic cells (BM-DCs) and splenic classic dendritic cells CD11c(+) cDCs secreted increased levels of IL-6 and TNF-α, at both baseline and following lipopolysaccharide (LPS) stimulation." (PMID 35010832, 2022). "Thus, taken together it may be speculated that the combinatorial effect of IL-17A/F and TNF-α may be a key contributing factor in facilitating neutrophilic inflammation in the lungs in severe asthma." (PMID 36517803, 2022).
asthma (continued). "In addition, according to the network pharmacology analysis, quercetin and ß-sitosterol had a strong binding ability to TNF, so they may be potential bioactive compounds of Danlong Dingchuan Decoction in treating asthma." (PMID 35186104, 2022). "Interestingly, ADAM28 might activate pathways leading to or supporting asthma-related inflammation by modulating the biological activity of mediators as TNF-α." (PMID 36685493, 2022). "In this case, after prolonged asthma, the expansion of this population may be an attempt to compensate for the excessive action of TNF by switching proapoptotic responses to proliferative ones, in turn inducing pathological hyperreactive proliferation characteristic of late stages of asthma." (PMID 36611799, 2022). "Interestingly, TNF blockade reduced IgE production to the level observed in mice with combined IL-6/TNF inhibition indicating a potential role for TNF-mediated signaling in modulation of the B-cell compartment in asthma." (PMID 35408882, 2022). "In all asthma patients, serum sTNF RI levels correlated with miRNA-106a (r = − 0.51, p < 0.001) and miRNA-126a (r = − 0.48, p = 0.004), while in EA, miRNA -126a was negatively correlated with TNF α (r = − 0.54, p = 0.005) and miRNA-146a was positively correlated with IL-8 (r = 0.45, p = 0.03)." (PMID 34112152, 2021). "Unfortunately, in a larger clinical phase 2 trial, golimumab, an anti-TNF, reduced asthma exacerbation risk in severe persistent asthmatics, did not improve asthma control and lung function, and actually provoked serious infections, such as pneumonia, and malignancies." (PMID 35055325, 2021). "The observation that IgE-activated cysLTs and TNF release is elevated upon MC response to viral dsRNA analog might be of great importance due to the known pathobiological role of these mediators in severe asthma." (PMID 32185237, 2020). "After given the anti-TNF-α, occurrence of asthma may be prevented." (PMID 32015750, 2020). "On the other hand, the apoptosis of epithelial cells may contribute to the promotion of epithelial shedding by activating not only the tumor necrosis factor-alpha- (TNF-α-) induced pathways, but also the mitochondrial pathways, which regulate the airway reflexes in asthma." (PMID 32411804, 2020). "Pharmacological inhibition of TNF-α activity with the monoclonal antibody infliximab, suppressed IL-4 production, adhesion molecule expression, and eosinophil infiltration in a mouse experimental model of allergic rhinitis, the pathology of which is similar to asthma." (PMID 32194407, 2020). "However, it is known that TNF-α is elevated in uncontrolled, severe asthma." (PMID 33134805, 2020). "In addition, IL4, IL8 and TNFα have been related with the pulmonary function in obstructive airway diseases and could be potential markers of asthma." (PMID 30986261, 2019). "Compared with helper T 2 (Th2) cytokines [IL-1β, IL-4, IL-5, and tumor necrosis factor-α (TNF-α)], helper T 1 (Th1) cytokines (IFN-γ and IL-12) are associated to antagonism of immunoglobulin E (IgE) synthesis and Th2 cell responses to restrain the progress of asthma." (PMID 31330806, 2019). "Lastly, activated TNF-alpha pathway in patients with severe asthma may continue to worsen T-regulatory (T-reg) function, which then results in an imbalance between T-reg cells and pathogenic Th17 and Th1 cells in the synovial cells, eventually leading to the development of RA." (PMID 29849649, 2018). "Local administration of TNF-α ASO remarkably inhibited TNF-α expression decreased inflammatory cell infiltration and blocked mucus hypersecretion, which was associated with increased CD4+CD25+FoxP3+ regulatory T cells and reduced Th2 cells in an OVA-induced murine asthma model." (PMID 28106744, 2017).
asthma (continued). "Interestingly, studies have shown that infection with RSV also results in a significant increase in proinflammatory cytokines such as interleukin (IL)-1, IL-6, IL-8, interferon (IFN)-γ, and tumor necrosis factor (TNF)-α, contributing to development of recurrent wheezing or asthma." (PMID 29246125, 2017). "Our data demonstrated that reinfected mice showed an increased production of IL-17A, IL-6, TNF-α, IL-4 and IL-5, suggesting a pattern of mixed Th2/Th17 responsiveness, which was previously observed in studies with helminths and also allergic disorders, such as rhinitis and asthma." (PMID 26814713, 2016). "TNFα 5′CGI may be a potential epigenetic biomarker for phthalate-induced asthma." (PMID 25960783, 2015). "Indeed, Th1 cells and the Th1-derived cytokines interferon-γ (IFN-γ) and tumour necrosis factor-α (TNF-α) are increased in patients with severe asthma, and these observations suggested that Th1 cells could mediate airway neutrophilic inflammation." (PMID 25878402, 2015). "Thus, it is tempting to speculate that the up-regulated TNF-α levels in severe refractory asthma may lead to prolonged eosinophil survival and thus to increased numbers of eosinophils in the blood circulation and tissues in vivo." (PMID 24587316, 2014). "Several studies in asthma have reported raised concentrations of factors in the airways that have the potential to chemoattract neutrophils and inhibit their apoptosis including, interleukin (IL)-8, IL-6, granulocyte-macrophage colony-stimulating-factor (GM-CSF) and tumour necrosis factor (TNF)-α." (PMID 24039773, 2013). "Also, omalizumab significantly reduced RNA and protein levels of IL-6, IL-8,TNFα and IL-4 in a dose-dependent manner in IgE-stimulated human airway smooth muscle cells isolated from biospsy specimens of patients with asthma, chronic obstructive pulmonary disease and healthy controls." (PMID 24004581, 2013). "TNFα could play a role in the pathogenesis of asthma by stimulating a number of responses in inflammatory cells and structural cells including the recruitment and activation of eosinophils, the activation of mast cells, and the upregulation of adhesion molecules on endothelial and epithelial cells." (PMID 22292924, 2012). "TNF-α blockers may also be useful particularly in severe asthma." (PMID 18315837, 2008). "In this case–parent triad study in a Mexico City population with high lifetime exposure to ozone, we found that the A allele of the functionally relevant TNF-308 polymorphism was significantly associated with an increased risk of childhood asthma, especially among children with nonsmoking parents." (PMID 17450233, 2007). "Similarly, the A allele of the TNF-238 SNP was associated with increased asthma risk among children of nonsmoking parents (RR = 2.21; 95% CI, 1.14–4.30; p for interaction = 0.01)." (PMID 17450233, 2007). "Despite the known effects of tobacco smoke on TNF expression and the well-documented association between parental smoking and childhood asthma, few studies have evaluated whether exposure to a smoking parent modifies effects of genetic variation in TNF on childhood asthma." (PMID 17450233, 2007). "Asthma patients showed greater decreases in CRP and TNF-α compared to infection or COPD groups, indicating that disease type has a substantial impact on treatment effects for inflammatory markers." (PMID 41555409, 2026). "Using a house dust mite (HDM)-induced murine asthma model and HDM, IL-4, IL-13, or TNF-α stimulated human primary bronchial epithelial cells (BECs) and bronchial epithelial (Beas-2b) cells, we modulated FAO with L-carnitine (agonist) and Etomoxir (inhibitor)." (PMID 41555513, 2026). "In conclusion, for patients with refractory EGPA with a history of “Type-2-low” asthma, particularly those who are ANCA-negative, TNF-α blockade can serve as an alternative treatment modality." (PMID 40703351, 2025).
asthma (continued). "Patients with asthma exhibit elevated serum levels of cytokines such as IL6, IL8, TNFα, and IL1β, which activate immune cells including neutrophils, macrophages, and lymphocytes, contributing to the initiation and development of inflammatory responses." (PMID 40598285, 2025). "A systems pharmacology approach has identified the capacity of baicalin to target 48 asthma-related genes such as IFNγ, IL4, IL5, IL10, IL13, and TNFα and signaling pathways, reinforcing its polypharmacological properties." (PMID 40598285, 2025). "The reduction in inflammatory factors such as TNF-α and IL-6, as well as the decreased expression of the important inflammatory pathway NF-κB/COX-2/PGE2, contributed to the effective control of asthma-related changes." (PMID 40323927, 2025). "The inflammatory process also increases the synthesis of proinflammatory cytokines such as interleukin (IL)-6, tumor necrosis factor-α (TNF-α), IL-1β, and transforming growth factor-β (TGF-β), all contributing to asthma pathogenesis and severity." (PMID 40083433, 2025). "Inflammatory cytokines, such as TNF‐α and IL‐1β, stimulate ASMC proliferation and contribute to the hyperresponsive airway phenotype in asthma." (PMID 40969143, 2025). "Th2‐low asthma includes neutrophilic asthma and paucigranulocytic asthma, also termed non‐type 2 inflammation, primarily mediated by neutrophils and involving pathways such as TH1, IFN‐γ/TNF‐α, and TH17." (PMID 41310922, 2025). "Publication bias was examined using funnel plots for asthma daytime and nighttime symptom scores, FEV1, FVC, PEF, and the levels of TNF-α, IL-4, and IFN-γ." (PMID 41561940, 2025). "Anti-TNF-α therapies target systemic inflammation and have been promising in restoring glucocorticoid sensitivity, especially in obesity-related GCI asthma." (PMID 40337626, 2025). "After establishing the asthma model, the levels of IL-5, IL-13, MCP-1, TNF-α, and eotaxin significantly increased in the PLA group compared with those in the NOR group (P < 0.01), while the IL-10 level significantly decreased by 42.0% (P < 0.01)." (PMID 39820222, 2025). "Our findings illustrated that in the serum of children with BA, miR‐27a‐3p targets ATF3 and inhibits ATF3 levels, promotes airway inflammation, and upregulates the levels of IL‐17, IL‐6, TNF‐a, and EOS, thereby promoting the occurrence of asthma." (PMID 37385291, 2025). "These components were subjected to molecular docking studies to evaluate their interaction with key asthma-related targets such as AKT1, TNF, and IL1B." (PMID 40420184, 2025). "In the experiment, after OVA stimulation, the levels of IL-4, IL-5, IL-13, and TNF-α in BALF and the level of IgE in the serum of mice in the asthma model group were significantly elevated, indicating that Th2 cells were overly active." (PMID 40563981, 2025). "Proinflammatory cytokines (TNF-α, IL-6) and profibrogenic mediators (TGF-β1, IL-13) also play significant and distinct roles in asthma pathogenesis." (PMID 40573126, 2025). "Ultimately, the molecular profile of Type 1 inflammatory asthma features a predominance of Th1 cells, increased levels of IFN-γ and TNF-α, and significant recruitment of neutrophils through chemokines such as IL-8 and CXCL1." (PMID 40564060, 2025). "The relevance between the FEO‐03 network and asthma on the KEGG Pathways database presented EPX, IL4, IL5, IL13, CD40LG, TNF, and IL10 according to p value." (PMID 40777200, 2025). "TNF-α, a key component of the TNF signaling system, plays a crucial role in asthma-related inflammation." (PMID 40165005, 2025). "Our molecular docking confirmed interactions of these active components, particularly Kaempferol and Norephedrine, with core targets AKT1, TNF, and IL1B, underscoring their potential therapeutic roles in managing asthma." (PMID 40420184, 2025).
asthma (continued). "To investigate the mechanism of necroptosis and TL1A in asthma, we established an in vitro cell model of airway epithelial necroptosis using TSZ (TNF-α, Smac mimetic, zVAD-fmk)." (PMID 38987753, 2024). "In respiratory diseases like asthma and COPD, NF‐κB, a central inflammatory mediator, can be activated by cytokines such as IL‐1β and TNF‐α." (PMID 39580709, 2024). "Direct targeting of the 3’UTR region of STAT3 by exosome miR-301a-3p reduced the release of inflammatory cytokines TNF-α, IL-1β, and IL-6, which can inhibit OVA-induced asthma." (PMID 39444792, 2024). "In contrast, the asthma population had higher levels of inflammatory factors, including C-reactive protein (CRP) and tumor necrosis factor alpha (TNF-α)." (PMID 39459579, 2024). "Notable genes that were differentially methylated based on asthma severity included RUNX3, several members of the HLA family, AGT, PTPRC, PTPRJ, and several genes downstream of the JAK2 and TNF signaling pathway." (PMID 39380119, 2024). "To further confirm the inference that shikonin can alleviate asthma by regulating STAT3, we observed the effect of shikonin on the expression and localization of p-STAT3 in TNF-α-induced mouse epithelial cell line MLE-12." (PMID 39444792, 2024). "Various stimuli induce type 1 T helper cells (Th1) to release tumor necrosis factor-α (TNF-α), which drives neutrophil recruitment and increases airway smooth muscle contraction, ultimately facilitating asthma progression." (PMID 39796021, 2024). "Small molecule inhibitors, such as JAK-inhibitors, and monoclonal antibodies targeting mast cells, IL-1, IL-6, IL-33, TNFα, and OX40L are under investigation for their potential to modulate inflammation involved in refractory asthma." (PMID 39194521, 2024). "We found that the mRNA expression of IL-13, TNF, IL-4, VEGFR2 and VEGF, were downregulated in the control, dexamethasone and vandetanib groups compared with the asthma group." (PMID 38799165, 2024). "Influenza viruses provoke elevated levels of pro-inflammatory cytokines, such as IL-6, TNF-α, and interferons, worsening airway inflammation and airflow limitation in COPD and asthma." (PMID 39458339, 2024). "Different cytokines were shown to play a key role in driving neutrophilic inflammation in asthma such as CXCL8, IL-17A or TNFα." (PMID 38892358, 2024). "Our results show that YPL-001 and its iridoids suppress the TNF/NF-κB/MUC5AC and PMA/PKCδ/EGR-1 cascades, which are important signaling pathways involved in inflammatory lung diseases, including COPD and asthma." (PMID 37108390, 2023). "Various experiments on the effects of NPs on lung disorders, such as asthma, COPD, and other lung diseases, indicated that nanoparticles suppressed proinflammatory mediators, such as IL-6, IL-8, IL-1β, and TNF-α." (PMID 37538179, 2023). "Inflammatory cytokines, such as TNF-α and IL-1β, increase ASM proliferation and contractile force to restrict airflow in asthma." (PMID 37445635, 2023). "In obese mice, intraperitoneal administration of anti-TNF- monoclonal antibody significantly decreased lung matrix metallopeptidase 9 (MMP-9) activity, demonstrating a link between TNF- and increased asthma severity in obese subjects." (PMID 37251328, 2023). "The top six upregulated DEG genes (IL6, CXCL8, TNF, DUSP2, ADM, and CXCL1) in SR asthma patients compared with SS asthma patients were identified." (PMID 37208441, 2023). "Studies have shown that ROS excess in airway epithelium increases asthma inflammation by releasing tumor necrosis factor (TNF) and IL-1, IL-6, and IL-8, especially with regard to severe asthma, asthma attacks, and asthma in obese subjects." (PMID 36671825, 2023). "TSLP, a pleiotropic cytokine, is a key factor in the pathogenesis of asthma, and elevated TSLP levels have been correlated with enhanced levels of TNF-α and Th2 cytokines." (PMID 37569890, 2023).